XIAP (X-linked inhibitor of apoptosis)
Diseases named in the same sentence as XIAP in open-access papers (continued):
Sharing a sentence is not in itself a finding about the gene and the disease.
tumor (continued). "There were statistically significant differences in XIAP immunoreactivity when comparing the various anatomical areas of tumor presentation." (PMID 41253834, 2025). "XIAP, in contrast, acts downstream in the apoptotic cascade by directly inhibiting effector caspases, thereby prolonging tumor cell survival." (PMID 41253834, 2025). "In GBM 8401-cell xenografted mice, tetrandrine decreases the expression of c-FLIP, MCL-1, and XIAP in tumor tissues." (PMID 40286187, 2025). "Early FDIM showed upregulation of genes linked to tumour initiation, immune recruitment, and motility (e.g., STOX1, PEG3, XIAP, MCAM, VIM)." (PMID 40683913, 2025). "As expected, XIAP:CASP7-proficient tumor cells have an increased dependence on 643943-mediated effects." (PMID 40533441, 2025). "Along with other IAPs, cIAP1 is an inhibitor of the extrinsic apoptosis pathway and supports tumor cell survival in a different manner than XIAP." (PMID 40940829, 2025). "More precisely, mRNA and protein levels of BCL-2 and XIAP were reduced in the presence of SAFit, suggesting that, by counteracting NF-κB activation, SAFit is able to turn off the survival pathways of the tumor." (PMID 40180895, 2025). "XIAP directly binds to and inhibits caspases-3, -7, and -9, thereby blocking the execution phase of apoptosis and promoting tumour cell survival." (PMID 41253834, 2025). "High XIAP expression is related to the molecular changes that occur during tumor progression, leading to higher histologic grades since it plays a significant role as an antiapoptotic protein that inhibits cell death." (PMID 41253834, 2025). "A novel NF-κB inhibitor, IT-901, induces significant cell apoptosis in primary RT cells and RT-PDX models by downregulating the expression of the anti-apoptotic protein XIAP and upregulating the pro-apoptotic protein Bim in tumor cells." (PMID 40565027, 2025). "X-linked inhibitor of apoptosis protein (XIAP), a member of the IAP family, is overexpressed in a variety of tumors and plays an important role in tumor progression." (PMID 40133252, 2025). "XIAP acts as a stress sensor during death stimuli, including when tumor cells are exposed to therapeutic agents, as it is translationally upregulated via a unique IRES element in its 5′ untranslated RNA30." (PMID 39075068, 2024). "For instance, dual-target inhibitors targeting MDM4/MDMX and XIAP have shown good tumor inhibition potential and avoidance of MDM2 feedback activation in both in vitro and in vivo models." (PMID 39215364, 2024). "Human and mouse studies have shown that ARTS functions as a tumor suppressor protein and physiological antagonist of XIAP in vivo." (PMID 38684550, 2024). "Recently, we and others have shown that some tumor cells undergo necroptosis following treatment with tolinapant, an antagonist of cIAP1/2 and XIAP." (PMID 38727208, 2024). "XIAP is known to promote tumor growth and progression by inhibiting cell death pathways via its E3 ubiquitin ligase activity." (PMID 38351372, 2024). "Deletion of Sept4 led to an increased number of hematopoietic stem cells or tumor-initiating cells, upregulation of XIAP, resistance to apoptosis, and, consequently, accelerated development of leukemias and lymphomas." (PMID 36565718, 2023). "We had previously shown that XIAP protein is upregulated in primary tumor cells from children with T‐ALL associated with poor prognosis and now studied the expression of XIAP on mRNA and protein level in both, children and adults with ALL." (PMID 36416169, 2023). "Since PDAC inflammatory microenvironment differs from other tumor entities, it is possible that XIAP’s immunosuppressive impact shows the described duality on individual tumors." (PMID 36472768, 2023).
tumor (continued). "Decreased miR-200c led to an enhanced stabilization of XIAP mRNA, followed by XIAP overexpression and enhanced tumor cell invasion and metastasis." (PMID 36845731, 2023). "Our data show that XIAP is required for growth of PDX r/r ALL samples in mice as silencing of XIAP decreased tumor load in a dose‐dependent manner." (PMID 36416169, 2023). "This highlights not only the effects on apoptosis but also the inflammatory cell response regulative function of XIAP, turning it into an interesting research target considering inflammatory tumor microenvironment properties." (PMID 36472768, 2023). "The inhibition of XIAP production promoted drug sensitivity and impeded tumor formation in an MM model of NOD/SCID mice." (PMID 37048103, 2023). "Similar to our previous report, wherein inhibition of XIAP expression inhibits IBC tumor cell motility, current data shows that the cluster of cells remain near the implantation site even after 5 days and do not spread like the parental SUM149 or SUM190 cells." (PMID 37190189, 2023). "Although a growing number of studies have demonstrated the role of XIAP in tumour initiation and progression, including haematological malignancies, little is known about the prognostic implication of its expression in AML." (PMID 37154878, 2023). "The cIAP1/2 and XIAP inhibitor Xevinapant inactivates all HNSCC tumor cells at higher concentrations and has much less effect on normal tissue cells." (PMID 37371123, 2023). "We previously identified the dominant role of anti-apoptotic protein XIAP in regulating tumor cell adaptive stress response (ASR) that promotes a hyperproliferative, drug resistant phenotype." (PMID 35697736, 2022). "In this current study, we found XIAP overexpression in 46.2% of PTC cases and it was associated with older age, advanced tumor stage and lymph node metastasis among other clinico-pathological parameters." (PMID 36578953, 2022). "XIAP siRNA can not only promote cell apoptosis but also inhibit the proliferation of tumor cells by regulating the cell cycle." (PMID 36430771, 2022). "Another research demonstrated that XIAP, and surviving cooperate to regulate the invasion of tumor cells and metastasis." (PMID 35992856, 2022). "AITC significantly downregulated the protein expression levels of MCL-1, XIAP, MMP-9, and VEGF; however, it increased apoptosis-associated proteins, such as cleaved caspase-3, -8, and -9, in the tumor tissues compared with the control group." (PMID 36142326, 2022). "Mechanistically, downregulation of circ_0003528 functions as a tumor suppressor by sponging miR-212-3p by targeting XIAP." (PMID 35484994, 2022). "XIAP is another important member of the anti-apoptotic gene family, which is highly expressed in many tumor cells and promotes tumor cell proliferation and anti-apoptosis." (PMID 35637953, 2022). "To identify the underlying mechanism of tumor growth inhibition, we further investigated the alteration of tumor-progression-related protein expression, including MCL-1, XIAP, MMP-9, and VEGF after AITC treatment by IHC staining of tumor tissues." (PMID 36142326, 2022). "Similar to XIAP expression, survivin expression has been correlated with worse clinicopathological features, such as metastasis, and advanced stage, or size, of the tumor." (PMID 35406442, 2022). "Upregulated circKIF5B level increased the mean immunopositive area for XIAP in tumor tissues, as determined by immunohistochemistry (IHC)." (PMID 35847962, 2022).
tumor (continued). "Meanwhile, treatment with BDMC up-regulated the expressions of BAX and cleaved caspase-3, while it down-regulated the protein expressions of Bcl-2 and XIAP in the tumor tissues compared with the control group." (PMID 35008959, 2022). "Pharmacological inhibition of IAPs using SMAC-mimetics in a humanized mouse model of EBV infection led to a reduction in circulating B cells, a phenotype primarily found in memory B cells of XIAP-patients and slightly reduced viral loads and tumor development." (PMID 36270981, 2022). "Altogether, these findings suggest that SLCO4A1-AS1 functions as a crucial oncogenic lncRNA in GC and it can facilitate GC tumor growth and metastasis by interacting with miR-149 and enhancing XIAP expression." (PMID 34650909, 2021). "Higher XIAP mRNA expression was associated (p < 0.05; Student t-test or one-way ANOVA test) with patients’ age ≤50 years, pathological ductal type, lower tumor grade, node-positive status, HR+/HER2− status, and PAM50 luminal B subtype." (PMID 34199946, 2021). "The apoptosis-associated protein expression in the tumor section was examined by immunohistochemical analysis, and the results showed that TET treatment reduced the levels of c-FLIP, MCL-1, and XIAP but increased the signals of cleaved-caspase-3, -8, and -9." (PMID 34885686, 2021). "We also evaluated the expression of β-catenin and its downstream proteins, XIAP and Survivin, in tumor tissues." (PMID 34294779, 2021). "Constrained lncRNA-SBF2-AS1 in M2 macrophage-derived exosomes increases miR-122-5p expression to reduce XIAP expression in tumour cells leading to tumour suppression." (PMID 34671031, 2021). "Toona sinensis crude extract decreased the incidences of SCCs, tumor number, tumor volume, and tumor burden in male Syrian golden hamsters by downregulating protein levels of survivin, XIAP, PCNA, iNOS, and COX-2." (PMID 34354591, 2021). "Expression of XIAP is also considered a prognostic marker since it corresponds with tumor combativeness and progression in renal cancer." (PMID 34712428, 2021). "XIAP targeting markedly enhances the cytotoxic activity of different cytostatic drugs in various tumor types, and antagonists of XIAP have been tested in patients with different kinds of tumors in clinical trials." (PMID 34025452, 2021). "Analysis of XIAP expression in tumor samples from 60 patients with advanced HNSCC, before and after chemotherapy, evidenced that XIAP is a predictor of cisplatin response and prognosis for patients with advanced HNSCC." (PMID 33718169, 2021). "Another study indicated intermolecular cooperation between IAP proteins, XIAP, and survivin to promote tumor cell invasion and metastasis centrally driven by NFκB activation." (PMID 34712428, 2021). "The log-rank test showed a significant inverse correlation (p = 0.0174) between XIAP expression and tumor aggressiveness in terms of patient survival." (PMID 34384473, 2021). "Currently, XIAP has been recommended as an appealing target for the latest anti-tumor interventions." (PMID 34712428, 2021). "First, we investigated the expression of Bcl-2 and XIAP, both of them were recognized as anti-apoptosis markers, which suppressed the tumor apoptosis effect." (PMID 34071132, 2021). "Usually, higher levels of XIAP are present in tumor tissues than in normal tissues, and it contributes to tumor cell survival, disease progression, and poor prognosis." (PMID 34650909, 2021). "Specifically, a significant increase of XIAP expression was observed from well (G1) to poorly (G3) differentiated ccRCCs (P < 0.0001) and from low (pT1) to advanced (pT3) tumor stages (P = 0.0016)." (PMID 34384473, 2021).
tumor (continued). "The in vivo pro-apoptotic effect of Sur-X was confirmed by the enhanced TUNEL staining and the decreased expression of survivin and XIAP in tumor tissues from xenograft mouse models." (PMID 32381104, 2020). "The majority of XIAP function studies in tumors, concluded that XIAP is key regulator, potentiating tumor cells to survive." (PMID 33138314, 2020). "XIAP, by inhibiting cell death and facilitating pro-survival pathways, promotes tumor initiation, promotion and progression." (PMID 33138314, 2020). "Whereas higher expression of SOX10, OCLN, ACSL4, XIAP, and ERCC5 was associated with a lower risk of death from the tumor (HR < 1)." (PMID 33153038, 2020). "XAF-1 is a pro-apoptotic tumor suppressor that can bind to and disrupt the anti-caspase activity of XIAP via sequestering XIAP31,33." (PMID 33130818, 2020). "The resulting survivin-XIAP heterodimers facilitate anti-proteasomal stability and inhibition of caspase-mediated apoptosis, thereby promoting tumor growth and survival." (PMID 32094363, 2020). "A study comparing miRNA mediated regulation of XIAP in non-neoplastic thyroid cells (Nthy-ori 3-1) and ATC cells (8305C) found that miR-618 targets XIAP expression, which results in inhibition of tumour growth." (PMID 33126409, 2020). "Mechanistic studies revealed that expression of various factors such as caspase-8, TNFα, RIP1, c-FLIP, FADD, cIAP1/2, and XIAP is essential for SM-mediated tumor cell death." (PMID 32325691, 2020). "XIAP is necessary for the constitutive activation of the NFkB pathway in IBC and the XIAP-NFkB axis directly correlates with the tumor growth rate in vivo." (PMID 32340135, 2020). "NF-κB has been shown to control the expression of tumor-related genes, such as Cyclin D1, c-Myc, HER2, interleukins, and XIAP, to regulate chronic inflammation, tumor cell survival, antiapoptosis, proliferation, invasion, and angiogenesis." (PMID 33282634, 2020). "Collectively, these results demonstrate the important physiological role of ARTS in regulating apoptosis and tumor suppressor in vivo through its role as a specific XIAP-antagonist." (PMID 32182843, 2020). "Collectively, these results demonstrate the important physiological role of ARTS in regulating apoptosis and as a tumour suppresor in vivo through its role as a specific XIAP antagonist." (PMID 32587235, 2020). "Expression of human IAPs was analyzed in the National Cancer Institute panel of 60 human tumor cell lines, and XIAP was found to be expressed in a majority of these cell lines." (PMID 33138314, 2020). "NF‐κB–associated proteins involved in tumour progression, such as MMP‐2, MMP‐9, uPA, VEGF, XIAP and Cyclin D1, were all decreased by imipramine." (PMID 32149465, 2020). "XIAP was stained by immunohistochemistry and correlated to clinical outcome, molecular markers and markers of the cellular tumor microenvironment." (PMID 31151416, 2019). "Based on these results, we concluded that the TCASS showed good application to tumours with high expression of XIAP." (PMID 31649241, 2019). "Tumours with high XIAP/low ATM levels have better PFS (p = 0.016) after platinum based chemotherapy." (PMID 31635307, 2019). "The key role of XIAP and its potential clinical relevance is well established in tumours and several XIAP inhibitors have been developed or discovered as cytotoxic agents." (PMID 31505859, 2019). "In vivo experiments further validate that tumor growth was stagnated after silencing of circ0005276 or XIAP." (PMID 31624242, 2019). "Further, the expression of XIAP and circ0005276 was detected in tumor tissues with different tumor stage and metastatic condition." (PMID 31624242, 2019). "Our findings suggest that the tumor microenvironment is crucially involved in the effect of tumor cell XIAP on patient’s outcome." (PMID 31151416, 2019).
tumor (continued). "Mice injected with XIAP-depleted tumor cells have more metastasis nodules in the lung, whereas co-depletion of Cdc42 and XIAP strongly inhibits lung metastasis." (PMID 31248165, 2019). "Immunoreactivities for XIAP, Bcl2, and Bax were mainly detected in cytoplasmic compartments and was heterogeneously distributed within tumor lesions." (PMID 30943930, 2019). "Under normal conditions, XIAP, an anti-apoptotic cofactor, binds to survivin in the mitochondria; however, the mitochondrial survivin-XIAP complex is released to the cytosol when tumor cells exposed to cell death stimuli." (PMID 31861751, 2019). "In summary, our studies reveal a novel Sp1/E2F1/miR-203/Src pathway that is responsible for the activation of MMP2 and the tumor-promotive role of XIAP in BC cell invasion." (PMID 31811115, 2019). "A recent series of studies, including ours, indicate that MDM2 is able to interact with other cellular molecules involved in tumor promotion and metastasis, such as XIAP, VEGF, and Akt." (PMID 31428819, 2019). "This demonstrates a novel aspect of XIAP as a key determinant of tumour control, at the molecular crossroad of caspase-dependent/independent cell death pathway and indicates molecular aspects to develop tumour-effective XIAP antagonists." (PMID 31505859, 2019). "tmTNF-α induced upregulation of NF-κB targeted antiapoptotic genes XIAP, cIAP1 and Bcl-XL, but downregulation of proapoptotic molecule BAX, which facilitates tumor cells evading apoptosis as another mechanism underlying tmTNF-α-induced chemoresistance." (PMID 29559745, 2018). "Further, we identified a mechanism of stress-induced protein translational upregulation of XIAP in promoting tumor cell survival in models of IBC." (PMID 30400822, 2018). "Mice with human ACC xenografts treated with flavopiridol and carfilzomib had significantly lower tumor burden, and increased cleaved-caspase and reduced XIAP expression in tumor xenografts." (PMID 30250647, 2018). "It was reported that tumor cells acquire TRAIL resistance by the upregulation of XIAP, c-FLIP, Bcl2, and Bcl-xL as antiapoptotic proteins, and activation of phosphoinositide 3-kinase (PI3K), protein kinase B (AKT), and NF-κB as proliferation activators." (PMID 29772677, 2018). "In a genetically engineered mouse model of PDAC, FG-3019 sensitized tumor cells to gemcitabine-induced apoptosis by inhibiting expression of XIAP." (PMID 29719620, 2018). "shRNA knockdown of tmTNF-α expression enhanced IκB-α levels, blocked p65 nucleus translocation, and reduced expression of cIAP1, XIAP, and Bcl-XL in the tumor tissues." (PMID 29559745, 2018). "We observed increased cleaved-caspase expression and decreased XIAP in tumor xenografts of mice treated with combined agents." (PMID 30250647, 2018). "NF-κB target gene encoding proteins such as MMP-9, VEGF, MCL-1, XIAP, C-FLIP, and Cyclin-D1, promote metastasis, angiogenesis, antiapoptosis, and proliferation in HCC leading to tumor progression." (PMID 29535278, 2018). "The process of tumor escape from apoptosis is believed to be the abnormal expression of XIAP in cells." (PMID 30594131, 2018). "XIAP can increase the apoptosis threshold, thus playing an important role in mediating tumor amplification and chemotherapeutic drug resistance." (PMID 30594131, 2018). "Since XIAP knockdown negatively impaired tumor growth of NEC-DUE cell lines in vivo, we took advantage of the well characterized smac mimetics Birinapant and GDC-0152 that have been demonstrated to selectively antagonize IAPs." (PMID 28039474, 2017). "Immunohistochemical analysis of the tumor sections revealed significant expression of NFκB (p65 subunit) in all the identified tumor embolic structures and XIAP expression in 8/14 samples with ranging degree of staining." (PMID 28460441, 2017). "Further, XIAP depletion promotes lung colonization of tumor cells in mice in a Cdc42-dependent manner." (PMID 28661476, 2017).